CDH1 (cadherin 1)
Diseases named in the same sentence as CDH1 in open-access papers (continued):
Sharing a sentence is not in itself a finding about the gene and the disease.
breast carcinoma (continued). "CDH1 facilitates metastasis in phenotypically sorted subpopulations of breast cancer cells, enabling clustering of circulating tumor cells." (PMID 35464064, 2022). "In BCCuS-low group, the mutation frequency of PIK3CA, CDH1, MAP3K1 up-regulated, these genes have been reported as tumor suppressor in breast cancer." (PMID 36699089, 2022). "Cdh1 (encoding E-Cadherin) has been reported to be transcriptionally regulated by FOXA2 in gastrulating endoderm as well as oral and breast cancer cells." (PMID 36398878, 2022). "To determine if the expression of Cdh1 is correlated with breast cancer, we analyzed the GSE115275 dataset." (PMID 35627188, 2022). "F-box and leucine-rich repeat protein 10 (FBXL10) interacting with SNAI1 promoted the migration and invasion of breast cancer cells by inhibiting CDH1 expression and inducing EMT." (PMID 35464064, 2022). "Knockdown of CDH1 in prostate cancer cell line PC-3 caused increased expression of the CD44 gene, as initially reported in breast cancer cells." (PMID 35493092, 2022). "CDH1/TGF-β/p-Smad2/3 signaling was found to be a survival axis in breast cancer by inhibiting reactive oxygen-dependent endogenous mitochondrial apoptosis." (PMID 35464064, 2022). "In the case of breast cancer, the CDH1 analysis should only be performed in the context of the rare lobular subtype, which then entails individualized prevention in the case of positivity." (PMID 35448173, 2022). "Apart from CDH1 and N-cadherin, VE-cadherin promotes the attachment of breast cancer cells to the endothelial layer and initiates the incorporation phase instead of transmigration." (PMID 35464064, 2022). "Caucasians with breast cancer and CRC were enriched for CDH1 germline variants compared to Caucasian controls from gnomAD." (PMID 34949788, 2022). "The −215 region of the CDH1 promoter has also been commonly targeted, with saRNAs designed around this region being shown to successfully upregulate CDH1 in renal carcinoma and breast cancer, and produce beneficial downstream phenotypic effects." (PMID 36700046, 2022). "The mesenchymal MDA-MB-231 breast cancer cell line had lower mRNA expression of epithelial marker CDH1 and higher expression of mesenchymal markers VIM and ZEB1 compared to the MCF-7 and MDA-MB-468 cell lines." (PMID 34207708, 2021).
breast carcinoma (continued). "A well-known example is that TWIST is a transcriptional repressor of CDH1 gene expression in contributing a malignant phenotype of breast cancer." (PMID 34357122, 2021). "The pathogenic variants of PTEN, CDH1, and STK11 were too rare in our study to estimate their risks of breast cancer in Chinese women, which suggested that these genes had a very limited contribution to breast cancer in unselected Chinese women." (PMID 34606182, 2021). "Our models also showed good results on predicting mutations of RB1 (AUC 0.852), CDH1 (AUC 0.776), NF1 (AUC 0.768), NOTCH2 (AUC 0.740) in breast cancer." (PMID 34556802, 2021). "In contrast to miR-200, miR-221 is an oncomiR, and its overexpression contributes to stemness maintenance in breast cancer by directly targeting CDH1, resulting in E-cadherin inhibition." (PMID 34360879, 2021). "Transcriptional inhibition of AhR was shown to induce expression of the tumor suppressor gene E-cadherin (CDH1), reducing the mesenchymal properties of breast-cancer cell lines." (PMID 33451095, 2021). "Previous experimental and computational efforts has suggested SLUG+CDH1+ cells would display a hybrid E/M phenotype, especially in breast cancer." (PMID 34975907, 2021). "It has been shown that the tumor tissues had higher rates of CDH1 hyper methylation compared with normal samples in Iranian breast cancer patients." (PMID 33883026, 2021). "Another study on Iranian breast cancer cases also showed a significant higher ratio of CDH1 promoter hyper methylation in tumors compared with normal tissues." (PMID 33883026, 2021). "This was confirmed by identifying ESR1 as the most frequent breast cancer cell-related factor binding to the CDH1 promoter sequence using the DB cistrome toolkit." (PMID 33420368, 2021).
breast carcinoma (continued). "For the cells driven by CDH1, CD4+ central memory T cell (Tcm) was proposed to be negatively associated with recurrence-free survival in breast cancer." (PMID 34368166, 2021). "The pathogenic variants of PTEN, CDH1, and STK11 were very rare, so they had a limited contribution to Chinese breast cancer." (PMID 34606182, 2021). "GRIK3 promotes epithelial-mesenchymal transition by regulating the SPDEF/CDH1 signaling in breast cancer cells." (PMID 33717664, 2021). "MCF7 cells (established from human Luminal A, ER+, PR+, HER2- breast cancer) express high levels of the epithelial cell marker E-cadherin (also known as Cadherin-1)." (PMID 32053991, 2020). "Given that atypical lobular hyperplasia (AL) and lobular carcinoma in situ (LCIS) are considered risk indicators for subsequent development of BC, we recommend an extensive sampling of the surgical specimen in CDH1 mutations carriers." (PMID 32560361, 2020). "The presence of CDH1 epigenetic and structural alterations in a diagnostic/pre‐operative biopsy may provide clinically useful information to improve patient management, particularly to infer the prognosis of breast cancer and the pattern of tumour dissemination." (PMID 32301282, 2020). "In MCF-7 and MCF10AT1 breast cancer cells, leptin downregulates CDH1 expression and upregulates SNAI2 expression through an autocrine mechanism that involves the expression and secretion of TGFB1." (PMID 33334030, 2020). "FOXQ1 has been reported to be implicated in breast cancer EMT and metastasis, negative regulation of CDH1 expression is one of the mechanisms." (PMID 32332873, 2020). "Overall, almost all the EMT genes analyzed were downregulated in breast cancer samples compared to normal breast tissues, except for CDH1, CTNNB1, and CDH2 that were upregulated in BC." (PMID 32911851, 2020). "To this end, we first characterized the expression of different cadherins (E-cadherin, N-cadherin, cadherin-11, and VE-cadherin) in a panel of breast cancer cell lines with different degrees of aggressiveness." (PMID 32752204, 2020). "Another close association of CDH1 mutation and invasive lobular breast cancer (ILBC) was found in the studies where risk of breast cancer was found in 39.9% of people and combined risk of 90% to develop diffuse gastric and ILBC by the age of 80." (PMID 33062523, 2020). "Pathogenic germline variants in CDH1 and CTNNA1 lead to a high prevalence of diffuse gastric cancer and breast cancer in carrier families." (PMID 33322525, 2020). "Among representative EMT markers, CDH1 expression was the most strikingly changed by fructose in breast-cancer cell lines." (PMID 33116123, 2020). "APC/C, Cdc20, Cdh1, βTrCP, and Skp2 are several E3 ligases that have been suggested to be potential therapeutic molecules in breast cancer." (PMID 32882786, 2020). "CDH1 drives proper cell cycle progression, and its depletion accelerates breast cancer cell proliferation and cooperates with PTEN loss to promote breast cancer progression in rodents." (PMID 33204396, 2020).
breast carcinoma (continued). "A correlation between CDH1 methylation status and the prognosis of breast cancer patients was also explored using a series of 137 primary breast cancers, 85 matched normal breast tissue samples, and 13 lung metastasis cases." (PMID 32301282, 2020). "Phosphorylated YWHAH promoted SLUG to repress the CDH1 gene, thereby leading to cell invasion in breast cancer." (PMID 33116123, 2020). "On the other hand, high levels of CDH1/E-cadherin and MAPK3/ERK1 have been associated with favorable prognoses in breast cancer, and Rsv increases their levels and/or activity in MCF7 cells." (PMID 33204396, 2020). "Here, the authors show that KHK-A mediates fructose-induced metastasis in breast cancer through a nuclear role in repressing the transcriptional activity of the cell-adhesion molecule CDH1." (PMID 33116123, 2020). "They observed that CDH1 promoter hypermethylation was preferentially observed in breast cancer cases with positive lymph node metastasis and in cases from more aggressive immunohistochemical subtypes." (PMID 32301282, 2020). "Tumor suppressor genes like p16, BRCA1, GSTP1, TIMP-4, and CDH1 contribute to breast cancer progression and growth." (PMID 32824813, 2020). "Cdh1/E-cadherin mRNA expression was marginally lower (P = 0.08) in E0771 mammary tumors from HFD offspring than in control offspring." (PMID 32580156, 2020). "Expression of Cdh1/E-cadherin was significantly downregulated before TAM treatment in the mammary tumors of HFD offspring (P = 0.025), compared with control offspring." (PMID 32580156, 2020). "Mammary tumors from control offspring had higher expression of Cdh1 before treatment, compared with TAM-treated (P = 0.005) and recurring tumors (P = 0.022; 2-way ANOVA for interaction: P = 0.003)." (PMID 32580156, 2020). "This ratio also applies to breast cancer cells based on the similar expression levels of Cdh1 and Src in multiple cell lines." (PMID 31420536, 2019). "We found that specific genes such as CBL, RHOA, EP300, RAC1, CDK1, and CDH1 are involved in the migration and invasion of breast cancer." (PMID 30930932, 2019). "In breast cancer, loss of E-cadherin is the hallmark of lobular carcinomas, whereas CDH1/E-cadherin mutations are the initiation event of hereditary diffuse gastric cancer." (PMID 31010154, 2019). "We also observed that the transient expression of Nr2f1 results in the reduction of CDH1 mRNA levels in three independent human breast cancer cell lines that display an epithelial phenotype (T47D, MCF7, BT474)." (PMID 30087437, 2019). "Whereas reconstruction of wild-type CDH1 in human breast cancer cell line MDA-MB-231 didn’t revert the morphology of the human cells, treating this cells with the ADAM10 specific inhibitor, GI 254023X showed a reduced migration without effecting cell numbers." (PMID 31105876, 2019). "The transcription factor ZEB2 has been predicted to be a transcriptional repressor of the CDH1 in human glioblastomas, breast cancer and renal cell carcinomas." (PMID 30645591, 2019). "Here, the authors show that reciprocal inhibition between Cdh1 and the c-Src signaling pathway regulate breast cancer tumorigenesis." (PMID 31420536, 2019). "Compared to control MDA-MB-231 and BT474 cells, depletion of Cdh1 promoted the proliferation of breast cancer cells." (PMID 31420536, 2019). "The in silico analysis of microarray datasets also suggested that the abundance of VAV2 and VAV3 transcripts is associated with low and high levels of CDH1 and NR2F1 transcripts in human breast cancer cell lines, respectively." (PMID 30087437, 2019).
breast carcinoma (continued). "For example, deletions in CDH1 and mutations in PIK3CA induce an immune subtype of breast cancer in a mice model." (PMID 31294536, 2019). "Heterogenous expression of SPDEF and CDH1 counteracted the migration and invasion abilities, respectively, of breast cancer cells induced by GRIK3." (PMID 30977227, 2019). "Further, while DNA methylation of CDH1 is an important mechanism for inhibition of E-cadherin protein expression in breast cancer cell lines, studies examining methylation of primary breast cancer tissues remain limited and are conflicting." (PMID 31533668, 2019). "Proximity ligation assay (PLA) and immunofluorescence analyses revealed that the majority of Cdh1 and Src are localized to the cytoplasm in breast cancer cells." (PMID 31420536, 2019). "HeLa, HEK293T, and breast cancer MCF7 cell growth was enhanced by CDH1 knockdown and TKTL1 overexpression, and exhibited inhibited growth after CDH1 overexpression and TKTL1 knockdown." (PMID 31175280, 2019). "This included 7 breast cancer-related genes: caspase 8 (CASP8), cadherin 1 type 1 (CDH1), estrogen receptor 1 (ESR1), ETS variant 6 (ETV6), forkhead box A1 (FOXA1), GATA-binding protein 3 (GATA3) and neurotrophic tyrosine kinase receptor type 3 (NTRK3)." (PMID 31182966, 2019). "Twist also associates directly with NuRD, in a different manner than Snail, to silence CDH1 transcription in mouse and human breast cancer cells." (PMID 31557902, 2019). "Our results have shown that different EMT phenotypes of CTCs (epithelial, epithelial-mesenchymal and mesenchymal) can be distinguished in CTCs-EBF of early breast cancer using a panel of 7 genes (MGB1/HER2/CK19/CDH1/CDH2/VIM/PLS3) tested in qPCR." (PMID 30634453, 2019). "Cadherin-1 and Catenin beta-1 have been already shown to interact with p140Cap in human breast cancer MCF7 cells." (PMID 31681758, 2019). "Profoundly, miR-23a promotes TGF-β1–induced EMT and cancer metastasis in breast cancer cells by directly targeting the cytoplasmic domain of E-cadherin (CDH1) and activating WNT/β-catenin signaling." (PMID 31126310, 2019). "The competition between forkhead box protein O1 (FOXO1) and E‐cadherin (CDH1) for miR‐9 was reported wherein FOXO1 acted as a ceRNA resulting in inhibition of metastasis of breast cancer cells by inducing CDH1 expression." (PMID 29603582, 2018). "Fukagawa and collaborators showed in a panel of breast cancer cell lines that CDH1 has different levels of methylation that correlate with ZEB1 and ZEB2 expression levels." (PMID 30445998, 2018). "We tracked the fates of co-cultured E and M clones and of fluorescent CDH1-promoter-driven cell lines reporting the E state derived from basal breast cancer HMLER cells." (PMID 29732000, 2018). "BRC-31 breast cancer cells expressed high levels of cdh2, fn1 and vim and low levels of cdh1 and krt-8 compared to BRC-17, 32, 36 and 196 cells." (PMID 29382358, 2018). "We show that Star-PAP and PIPKIα together regulate 3′-end processing and expression of pre-mRNAs encoding key anti-invasive factors (KISS1R, CDH1, NME1, CDH13, FEZ1, and WIF1) in breast cancer." (PMID 29203642, 2018).